C8orf82 (chromosome 8 open reading frame 82)
Synonyms: MGC70857
Tractability: PROTAC: its protein half-life has been measured.
Gene: Protein-coding gene on chromosome 8 (144,525,733 to 144,529,132, reverse strand). Ensembl gene ENSG00000213563.
Subcellular location (Human Protein Atlas): Nucleoplasm
Gene Ontology:
Cellular component: mitochondrion
Genetic constraint (gnomAD): Loss-of-function variants: 23 observed, 10.16 expected, observed/expected ratio (o/e) 2.26. The synonymous counts are far from expectation, so gnomAD's model fits this gene poorly and the ratio says little. Missense variants: 279 observed, 179.18 expected, observed/expected ratio (o/e) 1.56, 90% interval 1.41 to 1.72. Synonymous variants: 140 observed, 83.87 expected, observed/expected ratio (o/e) 1.67, 90% interval 1.45 to 1.9.
Homologues: Orthologues: chimpanzee C8H8orf82 (99% identical), macaque C8H8orf82 (95% identical), rat C7h8orf82 (88% identical), dog C8orf82 (86% identical), mouse C030006K11Rik (86% identical), pig C8orf82 (86% identical), guinea pig C8orf82 (83% identical), Drosophila melanogaster CG30010 (49% identical), Caenorhabditis elegans F59C6.12 (33% identical).
Diseases named in the same sentence as C8orf82 in open-access papers:
C8orf82 is named in the same sentence as 2 diseases in open-access papers, as found by Europe PMC text mining. Sharing a sentence is not in itself a finding about the gene and the disease. The quoted sentences say what the papers report.
cancer (1 paper, 2023). A tumor composed of atypical neoplastic, often pleomorphic cells that invade other tissues. "A search for novel genetic variants of C3orf70, C8orf33, C8orf76 and C8orf82 associated with systemic diseases, including cancers, is of practical interest for medical genomics." (PMID 37373333, 2023). "It is interesting to note that GA frequency is up to 6% in C3orf70, C8orf33, C8orf76 and C8orf82 genes according to the most affected cancer types." (PMID 37373333, 2023).
C8orf82 also shares sentences with these, for which no sentence is quoted: Cirrhosis (1 paper).